INS (insulin)
Diseases named in the same sentence as INS in open-access papers (continued):
Sharing a sentence is not in itself a finding about the gene and the disease.
Obesity (continued). "Obesity and chronic intestinal inflammation are already well documented in the literature, as well as their consequences in reducing insulin sensitivity and increased glucose uptake." (PMID 29950343, 2018). "The direct role of BCAAs in the stimulation of insulin secretion and correlations between elevated concentration of plasma BCAAs with obesity and serum insulin have been known for decades." (PMID 30101405, 2018). "Increasing the dietary amount of fat from 10 to 45% or 60% resulted in obesity accompanied by increased leptin, fasting blood glucose and insulin, and reduced glucose tolerance." (PMID 30670942, 2018). "In a recent study, AA showed an anti-obesity action in high-fat food fed rat model of obesity as evidenced by the improved antioxidant activities, regulation of lipid metabolism, and insulin and leptin sensitivity in addition to reduction in body weight gain." (PMID 30233358, 2018). "Decades of research ground the notion that localized immune cell infiltration in white adipose tissue (WAT), driven by the energy-surplus in obesity, promotes a low grade systemic inflammation which in turn induces a global impairment of insulin action." (PMID 30158466, 2018). "Although lifestyle changes remarkably improve insulin sensitivity and glucose homeostasis, these behavioral interventions suffer from poor compliance and are insufficient to overcome overt obesity and diabetes." (PMID 30275974, 2018). "Those mice were protected from high fat diet-induced obesity and fatty liver, and displayed profound insulin sensitivity and altered lipid profiles." (PMID 30274245, 2018). "In the Obesity and type 2 diabetes (T2D) study each subject was sampled at 4 time points: 0, 0.5, 1, and 2 h after insulin stimulation." (PMID 30541426, 2018). "Glucolipid metabolism disorder related to systemically upregulated chronic inflammatory responses and obesity is also characterized by increasing systemic inflammation and insulin resistance." (PMID 30463189, 2018). "Obesity also results in the progression of T2DM through deterioration of obesity-induced insulin resistance (IR), which is an inability of cells to respond to insulin properly." (PMID 29636788, 2018). "Depletion of glutathione also induces fat remodeling, enhances insulin sensitivity, and prevents obesity by HFD." (PMID 30304787, 2018). "Taken together, our results suggest that GL regulates the energy metabolizing process and lipid accumulation directly in the liver and adipocyte, and improves insulin sensitivity and the metabolic complications in a mouse model of diet-induced obesity." (PMID 29914094, 2018). "Obesity and dyslipidemia are considered to be the major factors contributing to the onset and development of HS, and hepatic lipid accumulation and insulin resistance are proposed to be the key factors contributing to steatosis development." (PMID 29971000, 2018). "Consumption of the high-fat diet for 10 weeks after weaning was effective in promoting obesity in the animals, impairing the glucose control and insulin responsiveness, and elevating the proinflammatory status." (PMID 30020947, 2018). "Insulin sensitivity was similar in the normal-weight and overweight groups whereas subjects with obesity had lower insulin sensitivity in comparison to normal-weight and overweight participants (both p < 0.05)." (PMID 29417372, 2018). "Adipocyte hyperplasia and hypertrophy play important roles in the modulation of insulin sensitivity, and impaired regulation of these processes has been reported in aging and obesity." (PMID 29746487, 2018). "During the postprandial state, reduced microvascular reactivity has been observed in obesity after a mixed meal, and this has been explained regarding impaired insulin sensitivity and postprandial hyperglycemia." (PMID 30515403, 2018).
Obesity (continued). "Transgenic overexpression of Cyp7a1 in mice increases bile acid synthesis, insulin and glucose tolerance, reduces inflammation and protects against HF diet induced obesity and steatosis." (PMID 30405201, 2018). "The frequent comorbidity of impaired insulin signaling with obesity suggests a mechanism whereby an obesogenic/diabetogenic diet, by blunting central insulin signaling, disrupts brain networks whose integrity requires optimal monoaminergic tone." (PMID 29698491, 2018). "Even though blood glucose levels in fasted state were not different among the groups, tolerance tests revealed that ADN and AMP improved the abnormal glucose tolerance and insulin sensitivity observed in the mouse model of obesity used in this study." (PMID 30428888, 2018). "In in vivo studies, PTP1B knockout mice exhibited elevated resistance to high-fat diet-induced obesity and insulin sensitivity." (PMID 30558294, 2018). "The chronic overconsumption of foods rich in carbohydrates and saturated lipids in obesity can affect insulin secretion and has a significant impact on cerebral glucose metabolism." (PMID 30042911, 2018). "In obesity, the most common insulin resistant condition, there is a compensatory pancreatic β-cell response against this hormonal resistance, which increases insulin secretion and maintains homeostatic glucose metabolism for a certain period of time." (PMID 30214428, 2018). "When obesity and hyperglycemia act in concert, the impairment in insulin secretion and signaling is highly potentiated, leading to a vicious circle of insulin resistance and β-cell dysfunction." (PMID 30336561, 2018). "Methylation loci associated with obesity (AEBP2), calcium signaling (CAPNS1), insulin signaling (INSR, PTPRN2, RPTOR) and vasodilation (VASP) also appeared to be epigenome-wide significant." (PMID 29692868, 2018). "It seems that increasing BAT activity and induction of browning by short-term cold exposure in humans can increase insulin sensitivity, but more work needs to be performed before it can be regarded as a suitable treatment of obesity and T2DM." (PMID 29697773, 2018). "Collectively, these data reveal that SWELL1 is post developmentally required for intact glucose-stimulated β-cell membrane depolarization, Ca2+-dependent insulin secretion and regulation of systemic glycaemia, particularly in the setting of mild obesity." (PMID 29371604, 2018). "Increased adiposity during obesity greatly influences insulin sensitivity, glucose and lipid metabolism, and inflammation." (PMID 30510798, 2018). "These mice were resistant to diet-induced obesity and had normal insulin sensitivity and adipogenic differentiation, however, they displayed impaired signalling through PPARγ and SREBP-1c." (PMID 30081476, 2018). "In the present study, we found that exposure of L6 myotubes to palmitate, to mimic the elevated plasma FFA levels seen in obesity in vivo, significantly decreased the insulin-stimulated glucose uptake indicating the induction of insulin resistance." (PMID 30400151, 2018). "Obesogenic diets often result in insulin resistance and a state of energetic stress in peripheral tissues and evidence indicates that obesity also alters brain insulin signaling and in turn energy status." (PMID 29890051, 2018). "Obese people with higher levels of basal irisin were shown to lose more weight with dieting and increased levels of irisin with early intervention in obesity have been reported to reduce insulin secretion and blood sugar level." (PMID 29809159, 2018). "We found for the first time that downregulation of B4GalT5 improved obesity-induced insulin sensitivity through regulating adipogenesis and M1 macrophage infiltration." (PMID 29415997, 2018). "Salidroside administration attenuated HFD-induced obesity, blood glucose variability, and hepatic lipid deposition, markedly increasing insulin sensitivity in HFD mice." (PMID 30140371, 2018).
Obesity (continued). "Metabolic factors of obesity, e.g. insulin, glucose and adipokines like leptin, and inflammatory factors have been related to the poor outcomes." (PMID 30034522, 2018). "This could include the changes in insulin sensitivity and glycemic control, given that impairments in these parameters have been implicated in explaining the lower fasting concentrations and blunted postprandial responses of appetite-related hormones in individuals with overweight/obesity." (PMID 30131457, 2018). "Circulating levels of FGF21, a potent insulin sensitizer and metabolism regulator, are elevated in mouse models of obesity although obese mice still respond to high doses of FGF21 by ameliorating glucose and lipid parameters (reviewed in20)." (PMID 30374109, 2018). "Disruption of insulin signaling in diet-induced obesity improves reproductive cyclicity in mice, suggesting that insulin represents a mediator for pituitary LH dysregulation in obesity." (PMID 29743077, 2018). "Liver-specific Sirt1 ko mice develop hepatic steatosis when underwent fasting and obesity when fed with HFD in insulin-dependent and independent manners." (PMID 30574122, 2018). "EVs from hypoxic adipocytes and also from subjects with obesity impaired insulin‐stimulated glucose uptake in vitro in cultured adipocytes." (PMID 29292863, 2018). "Variants associated with T2D have been shown to contribute to the development of the disease through different mechanisms, such as beta cell function, obesity, insulin secretion, obesity and hyperlipidaemia [6•, 15]." (PMID 29938349, 2018). "This diet profoundly decreased abdominal obesity, blood lipid levels, and increased hepatic insulin sensitivity among postmenopausal women with obesity." (PMID 29075849, 2018). "Nevertheless, the n-3 PUFA is capable of increasing insulin sensitivity by reducing the obesity inflammatory process, as well as the increase in adiponectin levels, which is reduced when there is an excess of adipocytes." (PMID 29320433, 2018). "In contrast with what is known of the action of mitoQ in obesity and insulin resistant states, little is known regarding the effect of mitoQ on pancreatic islet function." (PMID 29864244, 2018). "Obesity and female gender interacted in determining myocardial glucose uptake and insulin sensitivity, which demonstrated gender-related differences in the myocardial substrate metabolism due to obesity." (PMID 29631555, 2018). "This study aimed at evaluating the thyroid function and the effects of the triiodothyronine (T3) treatment on glycemia control, insulin sensitivity and subclinical inflammation in cafeteria‐diet‐induced obesity in rats." (PMID 29388360, 2018). "Note, liver-specific suppressor of cytokine signaling-3 deletion in mice enhanced hepatic insulin sensitivity but increased lipogenesis to result in fatty liver disease and obesity." (PMID 30547786, 2018). "Several molecular mechanisms, such as increased levels of estrogens by adipose tissue, inflammatory cytokines, insulin resistance, adipokines and oxidative stress, are involved in obesity-related pathogenesis of breast cancer." (PMID 30573731, 2018). "In another study, strength exercise did not change peripheral insulin sensitivity but improved the muscle mass and hepatic insulin sensitivity in youth with obesity." (PMID 29471797, 2018). "More than that, it positively correlates with the occurrence of obesity, high systolic blood pressure, and the plasma insulin level." (PMID 30383538, 2018). "The gut microbiota has recently been reported to disturb insulin signaling, which interferes with glucose regulation in obesity." (PMID 29636788, 2018). "Another study found that, in CCR2 knockout mouse, infiltration of macrophage in WAT due to HFD feeding-induced obesity was reduced and insulin sensitively was enhanced by comparison with wild type mice." (PMID 28168013, 2017).
Obesity (continued). "Specifically, women have a higher body fat percentage and insulin sensitivity, and the relationship between obesity and depression appears to be more pronounced in women." (PMID 29215576, 2017). "Surprisingly however, deletion of Mfn2 in mice fed a high fat diet (HFD) results in improved insulin sensitivity and resistance to obesity, while impaired cold‐stimulated thermogenesis is maintained." (PMID 28539390, 2017). "This indicates that high-fat-diet-induced insulin-dependent activation of VMH neurons contributes to obesity development." (PMID 28592656, 2017). "Other related obesity biomarkers including plasma lipid profiles, insulin, leptin, ghrelin and adiponectin levels also showed significant improvement (p < 0.05)." (PMID 28228098, 2017). "Overexpression of this miRNA in mice fed a high-fat diet enhanced insulin sensitivity and reduced hepatic glucose and fatty acid synthesis, so preventing obesity-induced metabolic complications." (PMID 28974990, 2017). "IPA analysis did not indicate a significant overlap of genes in the canonical pathways of which Leptin is a component, including Leptin signaling in obesity, insulin, or Jak/Stat." (PMID 28192065, 2017). "Several mouse models of obesity also revealed beneficial effects of IL-22 treatment on glucose homeostasis, insulin sensitivity, insulin secretion and inflammation." (PMID 28143481, 2017). "Reducing body weight with a very low calorie diet in patients with infertility and obesity resulted in an increase in insulin sensitivity that was inversely related to a decrease in luteinizing hormone." (PMID 29163369, 2017). "We show that BMT treatment indeed significantly decreased diet-induced obesity which involves altered characteristics of white adipocytes and a decreased insulin secretion in response to a HFD." (PMID 28445487, 2017). "During the first year after obesity surgery subjects lost a significant amount of weight and their fasting insulin concentrations improved (both P<5 × 10−8)." (PMID 28869586, 2017). "It acts as an endogenous insulin sensitizer and plasma concentrations are inversely correlated with obesity and metabolic syndrome." (PMID 28445413, 2017). "p66shc is involved in insulin signaling and its deletion exerts a protective effect against diet-induced obesity." (PMID 28740219, 2017). "Mice with impaired insulin sensitivity in response to TNF gain the capacity to be protected against obesity." (PMID 28884000, 2017). "Obesity changes the secretion of adipose tissue inflammatory cytokines, which modulate insulin signaling, so we analyzed the insulin signaling gene expression including insulin receptor (IR), insulin receptor substrate 1 (IRS-1), and IRS-2 in liver tissue." (PMID 29085434, 2017). "Common genetic variants at the ARL15 locus are associated with plasma adiponectin, insulin and HDL cholesterol concentrations, obesity, and coronary atherosclerosis." (PMID 29242557, 2017). "In conclusion, our findings suggest that miR-377 promotes white adipose tissue inflammation and decreases insulin sensitivity in obesity, at least in part, through suppressing SIRT1." (PMID 29050301, 2017). "We found that huREG3γtgIEC mice had a remarkable resistance to HFD-mediated obesity and reduced sensitivity to insulin and glucoses compared to WT littermate mice." (PMID 28928739, 2017). "It is widely accepted that the dynamic phase of obesity is indeed characterized by healthy AT expansion in response to increasing insulin level." (PMID 29242563, 2017). "Disruption of insulin secretion and clearance both contribute to obesity-induced hyperinsulinemia, though reduced insulin clearance seems to be the main factor." (PMID 29093479, 2017). "Using this new approach, we demonstrate a dose-dependent effect of STZ on circulating glucose and insulin levels as well as glucose tolerance, while retaining a state of obesity." (PMID 29075006, 2017).
Obesity (continued). "Hypothalamus inflammatory response after dietary fat-induced obesity is an important contributor in developing insulin and leptin resistance and defective food intake." (PMID 29281967, 2017). "Obesity and insulin treatment in dose-dependent and time-varying manner were associated with significantly increased risk of malignancy in females." (PMID 28978007, 2017). "The induced MS includes obesity, hypertension, dyslipidemia, insulin resistance (IR), hyperinsulinemia, and insulin secretion impairment." (PMID 28981461, 2017). "Despite obesity, female Mito-Ob mice maintained glucose homeostasis and insulin sensitivity similar to their wild-type littermates." (PMID 28432106, 2017). "When VEGFA is overexpressed in adipose tissue, it results in increased blood vessel number and size, protection against high-fat diet–induced hypoxia and obesity, and improves whole-body insulin sensitivity and glucose tolerance." (PMID 29196658, 2017). "CgA knockout mice (Chga-KO) display: (i) hypertension with increased plasma catecholamines, (ii) obesity, (iii) improved hepatic insulin sensitivity, and (iv) muscle insulin resistance." (PMID 28228748, 2017). "In adipocytes, insulin stimulates p66shc-dependent ROS production, which in turn regulates insulin signaling, sustaining triglyceride accumulation and obesity." (PMID 28740219, 2017). "Obesity status and obesity-related lifestyle factors are accompanied by elevated glucose metabolism traits (e.g., insulin, glucose, and HOMA-IR levels)." (PMID 28446149, 2017). "This indicates that presence of appropriate amounts of insulin and insulin receptors in the brain is essential to regulate appetite, obesity (BMI), maintain normoglycemia, and suppress inappropriate inflammation." (PMID 28824543, 2017). "Consistent with other changes, the presence of the CB1 receptor agonist increased the markers of obesity (weight gain and fat pad weight) and insulin resistance (oral GTT) in the HFD+C group." (PMID 28536285, 2017). "TNF-α, a proinflammatory cytokine, is increased in excessive insulin, obesity and metabolic syndrome." (PMID 29340106, 2017). "CXC Ligand 5 (CXCL5) is a new cytokine which inhibits the activity of insulin in muscles and promotes insulin resistance and secreted from white adipose tissue during obesity." (PMID 29387827, 2017). "Multiple factors affect muscle mass in patients with obesity including satellite cell function, inflammation, insulin signaling, and metabolic derangements." (PMID 28261159, 2017). "Fructose metabolism cannot be controlled by insulin or leptin, which are key factors for the regulation of fat synthesis and energy intake hence, obesity will likely be the consequence." (PMID 28129400, 2017). "Excitingly, we demonstrate in our diet induced obesity mouse model that neutralising ADAM19 therapy results in weight loss, improves insulin sensitivity, and reduces liver TNF-α levels." (PMID 28265178, 2017). "Together, these results demonstrate that IH per se can induce metabolic disorders in mice (including impaired insulin sensitivity and secretion), independently of any obesity." (PMID 28894286, 2017). "Changes in SORBS3 gene expression post-surgery were correlated with obesity measures and fasting insulin levels (r = 0.5 to 0.8; P < 0.05)." (PMID 28883895, 2017). "Currently, delta-6 desaturase activity was positively associated, whereas delta-5 desaturase activity was inversely associated with all adipose tissue depots, a pattern consistently observed in insulin resistant states and obesity." (PMID 28372558, 2017). "Compounds like gingerol have earlier been shown to have anti-obesity action and are reported for their beneficial influence on lipid profile, insulin, leptin, amylase and lipase in obese rats." (PMID 28804442, 2017).